LINC02897 (long independently transcribed non-coding RNA 2897)
Synonyms: FLJ45717; C1orf229
Gene: Long non-coding RNA gene on chromosome 1 (247,108,335 to 247,112,417, reverse strand). Ensembl gene ENSG00000221953.
Diseases named in the same sentence as LINC02897 in open-access papers:
LINC02897 is named in the same sentence as 2 diseases in open-access papers, as found by Europe PMC text mining. Sharing a sentence is not in itself a finding about the gene and the disease.
LINC02897 shares sentences with these, for which no sentence is quoted: malignant tumors (1 paper); Sepsis (1).